SEMA4D (semaphorin 4D)
Diseases named in the same sentence as SEMA4D in open-access papers (continued):
Sharing a sentence is not in itself a finding about the gene and the disease.
tumor (continued). "As an immune semaphorin, SEMA4D is able to regulate tumor microenvironment by differentiating monocytes toward tumor-supportive macrophage phenotype, namely, M2 macrophages with high expression of CD163." (PMID 34337054, 2021). "Sema4D mAb in combination with either CTLA-4 or PD-1 blockade enhanced rejection of tumors or tumor growth delay, resulting in prolonged survival with either treatment." (PMID 35003065, 2021). "Upon binding to its receptor, SEMA4D promotes activation and migration of endothelial cells and tumor cells." (PMID 33741032, 2021). "The expression of Sema4D has been described in tumor cells (TC) of several malignancies including HNSCC and by tumor infiltrating immune cells (IC), including tumor associated macrophages (TAMs)." (PMID 33776991, 2021). "The mechanism of action of this Sema4D-targeted antibody is not fully understood, since this semaphorin was reported to act on cancer cells and many other cell populations in the tumor microenvironment." (PMID 33537086, 2021). "SEMA4D was an oncogene and contributed to tumor progression in human patients or experimental models." (PMID 33957921, 2021). "Here we used Sema4D staining of the immune cells in the tumor microenvironment to score the three patterns of histological inflammatory subtype (INF, IE, ID)." (PMID 33776991, 2021). "Previous studies showed that inhibition of Sema4D in an in vivo tumor model facilitated IC infiltration into the tumors and decreased the MDSC component." (PMID 33776991, 2021). "qPCR showed that lycorine treatment significantly decreased the mRNA levels of two YAP-regulated tumor angiogenic genes, Sema4D and Ang2, in SPC-A-1 and A549 cells." (PMID 32439835, 2020). "Treatment of tumor-bearing mice with Sema4D mAb in combination with either CTLA-4 or PD-1 blockade enhanced the rejection of tumors or tumor growth delay, resulting in prolonged survival with either treatment." (PMID 32443699, 2020). "In fact, knocking out of Sema4D prevents tumor growth and metastasis in a breast cancer murine model (TSA cells)." (PMID 32555170, 2020). "Sema4D has been well studied with respect to human tumor progression, such as during apoptosis of vaginal epithelial cells." (PMID 31394878, 2019). "Sema4D has been reported to play an important role in the progression of apoptosis in several human and mouse tumor cells." (PMID 31394878, 2019). "Both cancer cells and TAMs have been found to express and release SEMA4D in the tumor microenvironment." (PMID 30658382, 2019). "Swiercz's study indicated Plexin-B1 stimulated tumor cell migration via tyrosine kinase receptor ErbB-2 pathway while antimigrated via met pathway, He believed that the effect of SEMA4D/Plexin-B1 mainly depended on the superior pathway." (PMID 30762724, 2019). "Sema4D and its receptor Plexin-B1 are commonly dysregulated in cancers, suggesting roles in cancer progression, invasion, tumor angiogenesis, and skeletal metastasis." (PMID 29971044, 2018). "A positive correlation between Sema4D+ve/high tumor cells and the pharyngeal location of HNSCC was detected (p=0.03)." (PMID 29541402, 2018). "A combination of anti-SEMA4D Ab with CTLA-4 Ab had a synergistic effect in complete tumor rejection, was more effective in tumor inhibition than anti-CTLA-4 Ab and anti-PD-1 Ab combination, and more significantly prolonged survival." (PMID 30134791, 2018). "Tumor growth inhibition by anti-semaphorin 4D (SEMA4D, CD100) blocking antibody is enhanced when combined with various immunotherapies in preclinical animal models." (PMID 30400822, 2018). "Total PD-L1+ve/high in tumor cells and TAIs were observed in 36% of 135 primary malignancies compared to 34% Sema4D+ve/high tumor cells." (PMID 29541402, 2018). "The cut off value to consider Sema4D+ve/high in tumor cells was strong diffuse positivity, that translated as 5x105 strong pixel intensity guided by the standardized digital analysis." (PMID 29541402, 2018).
tumor (continued). "Sema4D+ve/high tumor cells subtype was identified as a unique subset of HNSCC tumors distinct from the PD-L1+ve/high tumor cells, allowing for tumor stratification based on differential expression of Sema4D and PD-L1." (PMID 29541402, 2018). "Strong expression of Sema4D at the invasive margins of actively growing tumors changed the infiltration and distribution of leukocytes within the tumor microenvironment." (PMID 29971044, 2018). "In the tumor niche, Sema4D from the tumor cells and activated osteoclasts inhibits osteoblast differentiation, while inducing IL-8 secretion to further promote osteoclast proliferation and activity." (PMID 29971044, 2018). "The mechanisms by which Sema4D confers these features are complex and involve both tumor cells and their microenvironment." (PMID 29971044, 2018). "Neutralization of Sema4D by blocking antibodies disrupted this gradient of expression and enhanced recruitment of activated monocytes and lymphocytes into the tumor." (PMID 29971044, 2018). "SEMA4D blockade represents a novel approach to promote functional immune infiltration into the tumor, reduce mesenchymal suppression, and enhance immunotherapy effects." (PMID 30400822, 2018). "Plexin-B1 combines with SEMA4D secreted into the microenvironment from tumor cells to promote tumor angiogenesis and endothelial cell migration and vessel formation." (PMID 29308068, 2018). "Mechanistic studies in syngeneic preclinical models investigated the effects of SEMA4D blockade on anti-tumor activity and immune responses, both as a single agent and in combination with various immunotherapy agents." (PMID 30400822, 2018). "Sema4D+ve/high expression by tumor cells of primary HNSCC correlated directly with a dense fibrotic peri-tumoral stroma, representing 23% of the total cohort (p<0.0001)." (PMID 29541402, 2018). "In this study, we investigated the immunohistochemical expression of Sema4D by HNSCC tumor cells in correlation to clinical parameters and the peri-tumoral stromal phenotype." (PMID 29541402, 2018). "OE of SEMA4D in our model system decreased localized tumor growth but an increase in subarachnoid space spread was observed." (PMID 29377567, 2018). "Our data showed Sema4D+ve/high tumor cells in 34% of the studied cohort with positive correlation to Stage III (p=0.0001)." (PMID 29541402, 2018). "In HNSCC, Sema4D+ve/high expression in tumor cells correlated significantly with stage III HNC (p<0.0001)." (PMID 29541402, 2018). "We summarize the role of Sema4D/Plexin-B1 in cancers based on overexpression of Sema4D or Plexin-B1 by the cancer cells or by other cells in the tumor microenvironment including immune cells, and the role of Sema4D/Plexin-B1 in distant metastasis." (PMID 29971044, 2018). "To further investigate the Sema4D+ve/high HNSCC tumor cells with dense peri-tumoral stromal phenotype, we stained one TMA of 60 HNSCC for collagen." (PMID 29541402, 2018). "Sema4D affects both the activities of immune cells and their recruitment to the tumor microenvironment." (PMID 29971044, 2018). "Only one out of four metastatic SCC to lymph nodes had Sema4D+ve/high expression in the tumor cells, while the others were Sema4D-ve/low." (PMID 29541402, 2018). "In a head and neck cancer model, tumor-secreted Sema4D promoted the expansion of myeloid-derived suppressor cells, which inhibit T-cell functions." (PMID 29971044, 2018). "Since c-Met is one of the most commonly deregulated oncogene in cancers, its collaboration with Sema4D/Plexin-B1 is an alternative pathway to promote tumor invasion." (PMID 29971044, 2018). "Further phenotyping of the TAIs population in correlation to tumor staging and in correlation to Sema4D expression by tumor cells, will be important to confirm the suppressor cell phenotype versus other monocytic or lymphocytic cells." (PMID 29541402, 2018). "Herein, we also present evidence showing that Sema4D+ve/high tumor cells correlate significantly with stage III HNSCC." (PMID 29541402, 2018).
tumor (continued). "The data presented provide a novel role for Sema4D in the context of fibrosis and inflammation within the tumor microenvironment and demonstrate its value as a novel biomarker for HNSCC stromal phenotype." (PMID 29541402, 2018). "The Sema4D-Plexin B1 expression was found to be significantly related to tumor’s stage, depth of tumor invasion, lymph node metastasis, lymphatic invasion, and venous invasion, but unrelated to the patient’s age and gender." (PMID 30134791, 2018). "The data also showed 76% of the cases with dense peri-tumoral stroma to be Sema4D+ve/high in tumor cells." (PMID 29541402, 2018). "For example, anti-SEMA4D plus anti-CTLA-4 resulted in 90% complete tumor rejection (CR) (p<0.0001) in an HNSCC model representative of a T cell inflamed tumor with high MDSC suppression." (PMID 30400822, 2018). "In conclusion, we present a novel HNSCC tumor stratification model, based on the expression of the biomarker Sema4D." (PMID 29541402, 2018). "SEMA4D exerts multi-faceted effects within the tumor microenvironment by creating a barrier at the tumor-stroma margin to restrict immune cell infiltration and promoting immunosuppressive activity of myeloid-derived cells." (PMID 30400822, 2018). "Future studies in which Sema4D levels in plasma can be paired with stromal phenotype and level of expression in tumor cells, can be used to validate the potential of Sema4D as a stromal biomarker in the peripheral blood." (PMID 29541402, 2018). "We showed that high levels of Sema4D expression (Sema4D+ve/high) by HNSCC tumor cells significantly correlated with clinical staging, being highest in stage III." (PMID 29541402, 2018). "Sema4D also supports crucial steps in tumor progression, ranging from invasion, migration, angiogenesis, and immune suppression, to the pathological alteration of the tumor niche to support metastasis." (PMID 29971044, 2018). "Peripheral blood allowed for better healthy/normal control, as the tumor tissue controls were inflamed and positive for Sema4D." (PMID 29541402, 2018). "The authors concluded that SEMA4D inhibition represents a new therapeutic strategy aimed at inhibiting tumor progression by promoting functional immune cell infiltration into the tumor microenvironment." (PMID 30134791, 2018). "The normal tissue adjacent to tumor margin (NAT) was Sema4D positive to strongly positive (Sema4D+ve/high) in the basal and lower prickle cell." (PMID 29541402, 2018). "In a stratification model of HNSCC using combined Sema4D and the programmed death ligand 1 (PDL-1), Sema4D+ve/high tumor cells represented a phenotype distinct from the PDL-1 positive tumors." (PMID 29541402, 2018). "Recently, the role of Sema4D, via interaction with PlexinB1, in activities such as tumor angiogenesis and invasive growth have been discussed in relation to various types of tumors." (PMID 27456345, 2016). "Control MDA-MB-231 generated larger metastatic lesions (H&E stain) compared to those expressing Sema4D shRNA (upper right; BM: bone marrow; T: tumor)." (PMID 26910109, 2016). "The expression of Sema4D and PlexinB1 respectively were both found to be significantly related to stage, depth of tumor invasion, lymph node metastasis, lymphatic invasion, and venous invasion, respectively." (PMID 27456345, 2016). "The BLI results and histomorphometric analysis tend to support this model, as they describe a profile of decreased osteoblast function, enhanced osteoclast activity and larger, more numerous lesions when Sema4D is expressed in tumor cells." (PMID 26910109, 2016). "To determine the effects of tumor Sema4D on bone physiology we tested the serum from experimental animals by ELISA for markers of bone homeostasis and turnover." (PMID 26910109, 2016). "Interaction of Sema4D-expressing CD5+ B-cells or leukemic-B-cells with Plexin-B1-expressing cells led to improved tumor survival." (PMID 28003812, 2016).
tumor (continued). "Consistent with data obtained in tumour cells, Sema4D-induced ErbB-2 phosphorylation and RhoA activation in mouse osteoblasts were sensitive to the inhibition of the IKK-complex." (PMID 25137062, 2014). "In mouse models of breast cancer, TAM-produced Sema4D was found to be critical for tumor angiogenesis, vessel maturation, and tumor growth." (PMID 24634660, 2014). "In the tumor microenvironment, TAMs are the major source of Sema4D, which is critical for tumor angiogenesis and vessel maturation, as demonstrated by the impaired angiogenesis and vessel maturation in Sema4D knockout mice." (PMID 24782982, 2014). "Conversely, an important role of the SEMA4D-Plexin-B1 interaction in regulating different aspects of tumor progression and angiogenesis is well established." (PMID 25193853, 2014). "Subsequent studies show that Sema4D participates in axon guidance, angiogenesis and tumor progression, and that these events are mediated by a high affinity receptor, plexin B1, and possibly plexin B2." (PMID 23741311, 2013). "Similar findings were reported in human pancreas, where Sema4D-positive infiltrating lymphocytes interacted with plexin B1-positive tumor cells in pancreatic ducts." (PMID 23741311, 2013). "In contrast to these oncogenic roles of Sema4D, however, various lines of evidence point to a tumor suppressor role of its receptor plexin-B1." (PMID 23050142, 2012). "SEMA4D, a protein originally shown to regulate axonal growth in the developing nervous system, has been identified as promoting angiogenesis in tumor progression." (PMID 23202951, 2012). "Immunohistochemistry was used to analyze SEMA4D expression and tumor angiogenesis-related proteins (HIF-1α and VEGF) in tissues from 40 patients with normal ovarian epithelia and 124 EOC patients." (PMID 23202951, 2012). "Semaphorin4D (SEMA4D) has been regarded as an important protein in tumor angiogenesis, though originally identified in neurodevelopment." (PMID 23202951, 2012). "Other macrophage-derived molecules, such as IL-1β, cathepsin B, Wnt5a, and semaphorin 4D (Sema4D), have also been reported to promote tumor metastasis." (PMID 22778768, 2012). "Via interaction with its high affinity receptor Plexin-B1, Sema4D-Plexin-B1 involvement in tumor progression is strongly implied." (PMID 20858260, 2010). "Given its proangiogenic properties, the possible involvement of Sema4D in tumor angiogenesis was explored." (PMID 20858260, 2010). "Similar to other in vitro studies, tumor angiogenesis induction by Sema4D is mediated through its interaction with Plexin-B1." (PMID 20858260, 2010). "Here, we critically review and delineate the Sema4D-Plexin-B1 interaction in many facets of tumor progression: tumor angiogenesis, regulation of tumor-associated macrophages and control of invasive growth." (PMID 20858260, 2010). "Cumulative evidence regarding the roles of Sema4D- Plexin-B1 interaction in tumor progression came from in vitro and in vivo studies." (PMID 20858260, 2010). "By competing for Plexin-B1, these two molecules counter each other's effects in the same tumor cell, determining the net antimigratory or promigratory effect of Sema4D." (PMID 20858260, 2010). "In vitro and in vivo studies recently have given many insights into the involvement of Sema4D in tumor progression via interaction with Plexin-B1." (PMID 20858260, 2010). "In particular, PlexinB1, the receptor for Sema4D, has been suggested to play a role in neural development and in tumour angiogenesis, based on in vitro studies." (PMID 17519029, 2007). "Sema4D is a potent angiogenetic factor in vivo and it is released by many tumour cells [; and our unpublished data]." (PMID 17519029, 2007). "In mouse models, deletion of Sema4D significantly inhibits tumor growth and metastasis." (PMID 41163091, 2025).
tumor (continued). "The Plxnb2, which is a receptor for Sema4d, showed the highest expression in tumor epithelial cells, suggesting that the elevated levels of Sema4d in Mir34aΔMye CACs might have an impact on tumor cells towards increased invasiveness." (PMID 39425000, 2025). "However, in a neuroendocrine PC model, anti-Sema4D therapy, while inhibiting tumor growth and prolonging survival, unexpectedly promoted tumor invasiveness through retrograde signaling mediated by macrophages." (PMID 41163091, 2025). "PLXNB1, acting as the high‐affinity receptor for SEMA4D, might exert a more intricate function within the tumour microenvironment." (PMID 39443302, 2024). "Interestingly, in non-small cell lung cancer (NSCLC), there was an observed correlation between Sema4D expression and the development of perfused channels by tumor cells." (PMID 38375479, 2024). "Therefore, the observed associations between the expressions of the SEMA7A, SEMA4D, ADAM8, and ADAMTS10 in tumor groups with KRAS, NRAS, BRAF, PIK3CA, and AKT mutations require validation in larger study cohorts." (PMID 39329961, 2024). "Interestingly, the present study provides in vitro evidence that SEMA4D is involved in tumour progression and metastasis in CRC, and that its inhibition prevents the invasion and migration of HCT116 cells, which corresponds to the findings of previous reports." (PMID 39443302, 2024). "Sema4D produced by tumor cells may also act as an autocrine or paracrine signal to suppress migration; nonpolarized activation of Plexin-B1 over the whole cell results in cell collapse in vitro." (PMID 36936664, 2023). "In addition, we also investigated the effects of Sema4D knockdown on B16-F10R cells in response to nivolumab, downregulation of Sema4D also increased the inhibiting the growth of tumor cells and reducing cell invasion and migration." (PMID 37096066, 2023). "Thus, the immune reprogramming process induced by SEMA4D signaling between tumor cells and immune cells plays an important role in tumor immunity." (PMID 37287907, 2023). "SEMA4D widely mediates the suppressive tumor immune microenvironment." (PMID 37287907, 2023). "Real time fluorescent quantitative polymerase chain reaction (RT–qPCR), immunohistochemical (IHC) and flow cytometry (FCM) were used to further confirm the expression pattern of SEMA4D in TME and to explore the effect of SEMA4D in tumor-infiltrating lymphocytes." (PMID 37287907, 2023). "Therefore, SEMA4D plays a complicated role in the tumor microenvironment (TME) because it affects a wide range of immune cell populations and participates in stimulatory and inhibitory immune responses." (PMID 37287907, 2023). "We believed that the downregulation of SEMA4D expression as the tumor progresses might result from decreased immune cell infiltration." (PMID 37287907, 2023). "SEMA4D expressed on tumor cells very likely affects immune cells." (PMID 37287907, 2023). "Moreover, we verified the enhancement of anti-PD-1 sensitivity by Sema4D knockdown in vivo xenograft models, mice treated with nivolumab after Sema4D knockdown showed significantly slower tumor growth." (PMID 37096066, 2023). "It was reported in the relevant literature that inhibition of Sema4D in tumor cells not only inhibits tumor angiogenesis but also may restore T-cell immune activity specific to antigens." (PMID 36713527, 2022). "That HIS-IE tumor tissue correlated with HsS4D in plasma and positive Sema4D tumor cells." (PMID 36338570, 2022). "Interestingly, Sema4D significantly increased in the tumor cell upon treatment with OPN starting at a low concentration." (PMID 36338570, 2022). "SEMA4D is a classic member of the semaphorin family that is widely represented in the immune system and plays an important role in many physiological and pathological processes, including immunoregulation, angiogenesis, neurogenesis, and tumor progression." (PMID 35281072, 2022).